ICAM1 (intercellular adhesion molecule 1)
Diseases named in the same sentence as ICAM1 in open-access papers (continued):
Sharing a sentence is not in itself a finding about the gene and the disease.
cancer (continued). "Moreover, inhibition of acto-myosin contractility in CAF induces a decrease of ICAM-1 expression, which suggests that a positive feedback signaling mediates excessive ECM deposition and fibrotic tissue formation in cancers." (PMID 27901489, 2017). "Multiple cytokines signaling converge to ICAM-1 to promote and sustain proinvasive matrix remodeling, which makes membrane-bound ICAM-1 a potential target for therapeutic protocols for patients suffering from aggressive carcinoma." (PMID 27901489, 2017). "Indeed, ICAM-1 and VCAM-1 expression correlates with increased metastasis and determines malignant potential of cancer [29." (PMID 27409174, 2016). "In cancers, ADAR1 appears to decrease the levels of miR-221 and miR-222, which target the cell surface glycoprotein ICAM1 gene and whose overexpressions are involved in cancers like pancreatic cancer, papillary thyroid carcinoma, prostate carcinoma, and metastatic melanoma." (PMID 27999332, 2016). "However, the present study shows that resistin not only induces ICAM-1 and VCAM-1 expression in CRC cells but also mediates cancer cell adhesion to the endothelium." (PMID 26690142, 2015). "ICAM1 and VCAM1 are considered to be important in the process of malignant tumor growth." (PMID 26239324, 2015). "Both ICAM-1 and VCAM-1 play a crucial role in cancer metastasis." (PMID 26690142, 2015). "The most recognized aspect of these interactions is cancer cell adhesion to the peritoneum, which has been found to be controlled by the binding of cancer cell surface ligand CD43 to the HPMC-derived intercellular adhesion molecule-1 (ICAM-1)." (PMID 26284488, 2015). "Besides the classical role of ICAM-1 on cancer cell adhesion, our studies demonstrated role of VAP-1 on cancer cell adhesion." (PMID 24900957, 2014). "These interactions could involve endothelial adhesion molecules such as ICAM-1, VCAM-1 and E-selectin which have been shown to play an important role for the interactions between cancer cells and the endothelium monolayer." (PMID 24857933, 2014). "The interaction between ICAM-1/VCAM-1 and their respective ligand may facilitate the adhesion of cancer cells to the vascular endothelium, and subsequently aid in the promotion of metastasis." (PMID 24555415, 2014). "ICAM-1 and VCAM-1 are involved in cell-cell and cell-extracellular matrix (ECM) interactions, and they are mechanistically important for the extravasation of monocytes during inflammation and cancer cells during metastasis." (PMID 25156554, 2014). "Previously, we identified the role of ICAM-1 for cancer cell adhesion to the endothelium; therefore, we investigated here the role of ICAM-1 expressed on ECs on these adhesion mechanisms by using a specific anti-ICAM-1 antibody." (PMID 24857933, 2014). "Blocking VCAM-1 on the endothelium surface but not ICAM-1 and E-selectin was shown to abolish the effect of such ROS on cancer cell binding, implying that ROS mediates cancer cell adhesion via VCAM-1-dependent mechanism." (PMID 23460862, 2013). "In addition, the inhibition of oncogenic functions including the adhesion of cancer cells to endothelial cells, cell migration, and cell invasion by GJH occurred concurrently with the reduction of ICAM-1 expression." (PMID 22028734, 2012). "Genes that were upregulated by demethylation but not methylated included genes that have been described previously as TSGs in other cancer types (e.g. BAP1, IGSF4, RRM2 (Gautam and Bepler (2006)), PMAIP1, claudin-1; and ICAM1;)." (PMID 18195710, 2008). "Finally, we checked for the effect of TAK-981 on (i) TIGIT (inhibitory receptor) and DNAM1 (activating receptor), which compete for binding to PVR and Nectin-2 on cancer cells, and (i) LFA1, which binds to ICAM-1 and stabilizes NK interaction with their target cells." (PMID 40661051, 2026). "ICAM-1, an integrin ligand, is expressed on several malignant cells and may thus contribute to both cancer growth and cancer immunosurveillance by adaptive and non-adaptive immune arms." (PMID 40475782, 2025).
cancer (continued). "In addition, although ICAM‐1+/Ki67+ cancer cells survived ICAM‐1 treatment, they became exceedingly rare following ICAM‐1–Dxd treatment in organoid cultures, further validating the promising therapeutic potential of ICAM‐1–Dxd in the management of TNBC." (PMID 39996528, 2025). "FUT1 targets the fucosylation of CD147, intercellular adhesion molecule 1 (ICAM-1), EGFR, and EPH receptor A2 (EPHA2), consequently converging on the down-regulation of AKT/mTOR/eukaryotic translation initiation factor 4E-binding protein 1 (4EBP1) signaling to enhance cancer stemness." (PMID 40821120, 2025). "This targeting mechanism of ExoDS may be attributed to a variety of membrane receptors like integrin α and β chains (αMβ2), ICAM-1, MFG-E8, TNF, FasL, CD86, CD80, CD40, CD83, MHC-I, MHC-II, NKG2D, IL-15Rα, CD21, CD11c, and CCR7, which help mDC-derived exosomes identify cancer cells." (PMID 38903193, 2024). "Consequently, ICAM1 may potentiate SRC signaling, thereby promoting the malignant potential of cancer." (PMID 38907234, 2024). "Therefore, the correlation between CX3CL1 and ICAM‐1 or VCAM‐1 is explored in the present study, showing that only CX3CL1‐induced ICAM‐1 expression is observed, indicating that ICAM‐1 plays a vital role in CX3CL1‐induced cancer metastasis." (PMID 37082943, 2023). "Towards reinforcing adoptive cancer immunotherapy, a ‘Synthetic Immune Niche’ (SIN) strategy was recently developed by Adutler-Lieber et.al., based on the stimulation of T-cells by surfaces, coated with the chemokine C-C motif Ligand 21 (CCL21) and the Intercellular Adhesion Molecule 1 (ICAM-1)." (PMID 36937426, 2023). "However, the biological mechanisms of the interactions between TNXB-SDC4, THY1-(ITGAX+ITGB2), ICAM1-(ITGAX+ITGB2), and C3-(ITGAX+ITGB2) ligand-receptor pairs in cancer remain unclear and warrant further investigation." (PMID 37954130, 2023). "The aim of this section is not to provide a definitive explanation of the roles of ICAM-1 in all cancers but to highlight recent studies on a subset of cancers as examples of how ICAM-1 can act to promote cancer, to suppress cancer, or to act as a therapeutic target." (PMID 37237555, 2023). "Consequently, ICAM-1 may further accelerate SRC signaling, promoting the malignant potential of cancer." (PMID 35487888, 2022). "One important highlight is the observation that HDAC inhibition could improve cancer cells’ immune response via the regulation of the expressions of tumor antigens, including CD40, CD80, CD86, MHC, ICAM-1 and MICA/B, which drive the elimination of cancer cell proliferation through the immune system." (PMID 35158821, 2022). "Similarly, a lack of difference in ICAM-1 expression was observed for cancer ICAM-1 expressing cells with different Egfl7-statuses." (PMID 35630004, 2022). "ICAM-1 is expressed on the surface of several malignant cells and may thus contribute to both cancer growth and cancer immunosurveillance by adaptive and non-adaptive immune arms." (PMID 35911772, 2022). "Second, as ICAM-1 acted as an adapter protein to regulate the c-MET-SRC axis in CRC, further research is required to determine whether it acts as an adapter protein in other types of cancer." (PMID 35487888, 2022). "Moreover, it was observed that ICAM1 and NTS are common to G1 and G3 cancer." (PMID 34768392, 2021). "Moreover, MAs upregulated α5β1 integrin expression on PFBs but not on PMCs or cancer cells, vimentin expression in all cells tested, and ICAM-1 only in cancer cells." (PMID 33921783, 2021). "The clazamycins, jenamidine A, dibohemamines D–F, and quinohemamine are all reported to be cytotoxic against a variety of cancer cell lines, and both bohemamine and NP25302 inhibit HL-60 cell adhesion to Chinese hamster ovary cells expressing intercellular adhesion molecule ICAM-1 (CD-54)." (PMID 33828615, 2021).
cancer (continued). "Beyond immunotherapeutic treatment in clinical trials in the upcoming future, other patients without malignant tumor could also benefit from immunotherapy targeting ICAM1." (PMID 34408980, 2021). "cGAS-driven extracellular export of 2′3′ cGAMP by cancer cells activates STING signaling in endothelial cells and cooperates with type 1 interferon to increase vascular permeability and expression of E selectin, VCAM-1, and ICAM-1 and T cell adhesion to the endothelium." (PMID 33013881, 2020). "Furthermore, cisplatin treatment has been shown to induce ICAM-1 expression in cancer cells; thus, it is not surprising that ICAM-1 is found at lower levels in the cisplatin-resistant cells compared to the OAC cisplatin-sensitive cells." (PMID 30791601, 2019). "Next, to assess whether expression of ICAM-1 changes with cancer progression, the inhibitory effect of ICAM-1 in metastatic or non-metastatic cancer cells was investigated." (PMID 29137327, 2017). "In addition to epidermal renewal, IngMeb also activates Protein Kinase C -delta (PKC-δ) which has been found to induce apoptosis in cancer cell lines and induce upregulation of neutrophil mediators, (IL-8, TNF-α, ICAM-1, and E-selectin), resulting in massive neutrophil invasion to the skin." (PMID 27636884, 2016). "Adhesion molecules, such as intracellular adhesion molecule-1 (ICAM-1), vascular cell adhesion molecule-1 (VCAM-1), E-cadherin and E-selectin plays a central role in endothelial adhesion of a number of cancer cells and are closely related to cancer invasion and metastasis." (PMID 27834913, 2016). "In GBM cells, ICAM-1 expression has been shown to increase following stimulation with proinflammatory cytokines, such as interleukin-1β (IL-1β), tumor necrosis factor-alpha (TNFα), and interferon-gamma (IFN-γ), indicating that ICAM-1 is one of the inflammatory mediators also in this type of cancer." (PMID 26798546, 2015). "The cell adhesion molecules (CAMs), such as vascular cell adhesion molecule-1 (VCAM-1), intercellular adhesion molecule-1 (ICAM-1) and endothelial cell selectin (E-selectin), which expressed by endothelial cells may play a critical role in the cancer metastasis." (PMID 25823660, 2015). "Hence, ICAM-1 and VCAM-1 in both cancer and endothelial cells may play synergistic roles in metastasis progressions." (PMID 26690142, 2015). "Thus, the issue of whether the resistin-initiated endothelial adhesion of CRC cells through ICAM-1 and VCAM-1 in CRC cells is controlled by cancer cell-leukocyte interactions warrants further investigation." (PMID 26690142, 2015). "However, recent studies reported a controversial role of ICAM-1, that is, its activation is necessary to induce the tissue inhibitor of matrix metalloproteinases-1 (TIMP-1) and a subsequent decrease in the extent of cancer cell invasiveness." (PMID 23573150, 2013). "To confirm the role of hydrogen peroxide and hydroxyl radical on cancer-endothelial cell interaction and to define the affected adhesion molecules, we blocked the endothelial surfaces with specific antibodies against VCAM-1, ICAM-1 and E-selectin, prior to cancer cell adhesion." (PMID 23460862, 2013). "Thus, ICAM-1 may play a critical role in tumorigenesis, and determining the critical role of ICAM-1 disruption may prevent cancer cell metastasis in disease development." (PMID 23803661, 2013). "This is not the first proof that ICAM-1 is an important mediator in cancer metastasis." (PMID 23803661, 2013). "However, adhesion molecules such as intercellular adhesion molecule 1 (ICAM-1), vascular cell adhesion molecule 1 (VCAM-1), and selectins aid TILs in adhesion to epithelial cells and create a TME that favors the host cell in the fight against cancer-infiltrating cells." (PMID 40872475, 2025).
cancer (continued). "The pro-tumoural effects of MCP-1, proliferin, TIMP-1 and soluble ICAM-1 whilst the anti-cancer effects of IGFBP-2, endostatin and ADAMTS-1 have been published and suggest that this secretome signature may well provide a combination of effects on cancer growth." (PMID 33730293, 2021). "Additionally pre-clinical results such as ICAM-1-specific PET imaging may provide future patients with prognostic and predictive data to inform care, or novel techniques such as electroporation may help overcome the challenges of the cancer microenvironment." (PMID 34681719, 2021). "However, consistent with the very low expression of ICAM-1 in HCT116 and HCT116-AA cells, the HCT116-AA supernatant was less effective in promoting cancer cell survival under acidic pH, suggesting that autocrine effect of CRC-AA cells may not apply to all cancer cells." (PMID 34987705, 2021). "Since ICAM-1 is a general adhesion molecule and may be recognized by other T cell subtypes, such as αβ T cells, it is possible that a similar ICAM-1-dependent mechanism may be involved in the interaction between cancer and αβ T cells in an MHC-restricted manner." (PMID 33846331, 2021). "However, a hypoxic environment is not necessarily favorable for the ICAM-1 mediated response, as vessel permeabilization factors released from cancer cells may also lead to generation of aberrant vasculature." (PMID 28417928, 2017). "Finally, we have introduced the non-trivial role of exosomes harboring LFA-1 or ICAM-1 in cancer." (PMID 29099772, 2017). "Furthermore, the spreading carcinoma cells may have some capability in escaping the immune surveillance since TNF-α has not been found to induce ICAM-1 and HLA class 1 and 2 antigens in SiHa and CaSki cells." (PMID 18257926, 2008). "Similarly, vital immune checkpoint genes such as HAVR2, CD274, CTLA4, ITGB2, ICAM1, CCL5, CXCL10 all exhibited robust correlation with IFI30, and this immunotherapy might, in the future, establish a bond with IFI30, bringing new opportunities for cancer treatment." (PMID 39925804, 2025). "The overall effects of exercise on circulating ICAM-1, VCAM-1, and MCP-1 in cancer patients were small and nonsignificant." (PMID 41583457, 2025). "And the glycogen riskScore was significantly positively related with immunoinhibitors TGFB1, ICAM1 and CD276, and showed significantly negative relationship with immunostimulators TNFSF14 across pan-cancer." (PMID 39895799, 2025). "The relationship between ICAM1, TTN (Titin), and SYNE1 (Spectrin Repeat Containing Nuclear Envelope Protein 1) in cancer is not extensively studied, and their direct interplay in cancer is not well established." (PMID 37671167, 2023). "A decrease in expression regardless of cancer grade was observed for CALM2, DRD5, ICAM1, while EGR1, HRH1, HRH2, HRH3 were overexpressed." (PMID 34768392, 2021). "Although functional association between ICAM1 and CDDP sensitivity has not been fully characterized, an earlier study showed that the combination of CDDP + 5-fluorouracil synergistically induced ICAM1 expression in cancer cells, which may facilitate recognition of cancer cells by T lymphocytes." (PMID 29849953, 2018). "For the less invasive cancer cells (RT112), endothelial ICAM-1 does not seem to play any role in the adhesion process." (PMID 24857933, 2014). "Exposure to radiation induced significant cell-surface expression of MHC I (3/3 cell lines), ICAM-1 (3/3), CEA (2/3), and MUC-1 (3/3), regardless of carcinoma type." (PMID 24480782, 2014). "The downregulation of ICAM‐1 did not affect the proliferation of CT26 and 4T1 cancer cells." (PMID 37097643, 2023). "EGFL7 expression in cancer cells was observed in 6/47 (12.77%) ICAM-1-positive and in 3/12 (25.00%) ICAM-1-negative tumors; ICAM-1 scores were also similar whether EGFL7 was expressed or not." (PMID 35630004, 2022).
cancer (continued). "HC did not impair ICAM-1 expression, except form a minor reduction in FM55m1 and HT-29 cells, suggesting that citrate flux is essential for MICA expression in certain cancer cells." (PMID 32849657, 2020). "For naïve T cells, subsequent firm binding was established by ICAM-1 and ICAM-2; however, for cancer cells, this binding could not be blocked by anti-ICAM-1 and ICAM-2 antibodies." (PMID 24766770, 2014). "Although the mechanism and regulation of WISP1 SNPs in cancer progression have not been extensively investigated, the WISP1 SNPs of rs16893344 and rs2929970 might be involved in WISP1 regulation through WISP1-induced ICAM-1 upregulation and VEGF-A expression." (PMID 28426731, 2017). "However, there is no detailed information about whether resistin induces ICAM-1 and VCAM-1 expressions in cancer cells, and hence promotes its adhesion and invasion of the endothelium." (PMID 24555415, 2014). "Therefore, although we have not yet determined the precise role of ICAM-1 and VCAM-1 expression in CRC cells, ICAM-1 and VCAM-1 in the resistin-treated cancer and endothelial cells may be secreted into the cancer microenvironment and mediate the interactions of cancer, immune, and endothelial cells." (PMID 26690142, 2015). "In addition, our study showed that though the adhesion behavior of a type of cancer cells (e.g., MIA-PaCa-2) can be similar in various EC cultures, the mechanism controlling the adhesion might be different (i.e., effect of VAP-1 and ICAM-1 in the TMNK-1 but not in the HUVECs culture)." (PMID 24900957, 2014).